PTPRJ (protein tyrosine phosphatase receptor type J)
Description:
Tyrosine phosphatase which dephosphorylates or contributes to the dephosphorylation of CTNND1, FLT3, PDGFRB, MET, KDR, LYN, SRC, MAPK1, MAPK3, EGFR, TJP1, OCLN, PIK3R1 and PIK3R2. Plays a role in cell adhesion, migration, proliferation and differentiation. Has a role in megakaryocytes and platelet formation. Involved in vascular development (By similarity). Regulator of macrophage adhesion and spreading (By similarity). Positively affects cell-matrix adhesion (By similarity). Positive regulator of platelet activation and thrombosis. Negative regulator of cell proliferation. Negative regulator of PDGF-stimulated cell migration; through dephosphorylation of PDGFR. Positive regulator of endothelial cell survival, as well as of VEGF-induced SRC and AKT activation; through KDR dephosphorylation. Negative regulator of EGFR signaling pathway; through EGFR dephosphorylation. Enhances the barrier function of epithelial junctions during reassembly. Negatively regulates T-cell receptor (TCR) signaling. Upon T-cell TCR activation, it is up-regulated and excluded from the immunological synapses, while upon T-cell-antigen presenting cells (APC) disengagement, it is no longer excluded and can dephosphorylate PLCG1 and LAT to down-regulate prolongation of signaling. [Isoform 2]: Activates angiogenesis and cell migration. Downregulates the expression of the endothelial adhesion molecules ICAM1 and VCAM1.
Synonyms: R-PTP-eta; R-PTP-J; CD148; DEP1; HPTPeta; HPTP eta; SCC1; THC10
Tractability: Antibody: UniProt places it where antibodies can reach, with high confidence; its Gene Ontology location is reachable by antibodies, with high confidence; UniProt predicts a signal peptide or a membrane-spanning region. PROTAC: ubiquitination databases record sites on it; its protein half-life has been measured.
Target class: Enzyme; Protein Phosphatase; Receptor tyrosine-protein phosphatase; Tyrosine protein phosphatase; Phosphatase
Gene: Protein-coding gene on chromosome 11 (47,980,425 to 48,170,839, forward strand). Ensembl gene ENSG00000149177.
Subcellular location: Cell membrane; Cell projection, ruffle membrane; Cell junction; Secreted, extracellular space (Isoform 2)
Subcellular location (Human Protein Atlas): Cell Junctions; Nucleoplasm; Nuclear bodies; Nucleoli; Predicted to be secreted
Pathways (Reactome):
Immune System: Negative regulation of FLT3; Neutrophil degranulation; Phosphorylation of CD3 and TCR zeta chains
Signal Transduction: Negative regulation of MET activity
Gene Ontology:
Molecular function: beta-catenin binding; cadherin binding; delta-catenin binding; gamma-catenin binding; mitogen-activated protein kinase binding; phosphatase activity; platelet-derived growth factor receptor binding; protein binding; protein kinase binding; protein tyrosine phosphatase activity
Biological process: negative regulation of cell growth; negative regulation of cell migration; negative regulation of cell population proliferation; negative regulation of epidermal growth factor receptor signaling pathway; negative regulation of MAP kinase activity; negative regulation of phosphatidylinositol 3-kinase/protein kinase B signal transduction; negative regulation of platelet-derived growth factor receptor signaling pathway; negative regulation of T cell receptor signaling pathway; negative regulation of vascular permeability; peptidyl-tyrosine dephosphorylation; platelet formation; platelet-derived growth factor receptor signaling pathway; positive chemotaxis; positive regulation of cell adhesion; positive regulation of focal adhesion assembly; positive regulation of phosphatidylinositol 3-kinase/protein kinase B signal transduction; regulation of cell adhesion; axon guidance; B cell differentiation; contact inhibition; cytokine-mediated signaling pathway; positive regulation of calcium-mediated signaling; positive regulation of Fc receptor mediated stimulatory signaling pathway; positive regulation of MAPK cascade; positive regulation of phagocytosis; and 10 more
Cellular component: cell junction; cell surface; cell-cell junction; extracellular exosome; immunological synapse; plasma membrane; specific granule membrane; anchoring junction; extracellular region; ruffle membrane
Genetic constraint (gnomAD): Loss-of-function variants: 117 observed, 130.77 expected, observed/expected ratio (o/e) 0.89, 90% interval 0.77 to 1.04. The upper end of that interval is the gene's LOEUF score, 1.04, which puts it in group 4 of 6, group 1 being the genes least tolerant of losing a copy. Missense variants: 1,525 observed, 1,680.4 expected, observed/expected ratio (o/e) 0.91, 90% interval 0.87 to 0.95. Synonymous variants: 593 observed, 642.33 expected, observed/expected ratio (o/e) 0.92, 90% interval 0.86 to 0.99.
Gene-disease validity (ClinGen):
ClinGen rates the evidence that PTPRJ causes each of these diseases.
hereditary nonpolyposis colon cancer (autosomal dominant): Limited.
thrombocytopenia 10 (autosomal recessive): Limited.
Homologues: Orthologues: chimpanzee PTPRJ (97% identical), macaque PTPRJ (92% identical), rabbit PTPRJ (72% identical), pig PTPRJ (70% identical), rat Ptprj (68% identical), mouse Ptprj (67% identical), dog PTPRJ (64% identical), guinea pig PTPRJ (61% identical), zebrafish ptprja (32% identical), zebrafish ptprjb.1 (15% identical), zebrafish ptprjb.2 (14% identical). Paralogues in human: PTPRB (27% identical), PTPRH (22% identical), PTPRO (19% identical), PTPRS (19% identical), PTPRD (18% identical), PTPRF (18% identical), PTPN13 (18% identical), PTPRT (17% identical), PTPRM (17% identical), PTPRZ1 (16% identical), PTPRK (16% identical), PTPRU (15% identical), and 23 more.
Diseases named in the same sentence as PTPRJ in open-access papers:
PTPRJ is named in the same sentence as 84 diseases in open-access papers, as found by Europe PMC text mining. Sharing a sentence is not in itself a finding about the gene and the disease. The quoted sentences say what the papers report.
breast carcinoma (12 papers, 2009 to 2022). "It is suggested that PTPRJ is associated with increased recurrence and reduced survival in breast cancer patients." (PMID 36611803, 2022). "PTPRJ is a tumor suppressor and the rs1566734 mutation in PTPRJ has been linked to lung, colon and breast cancer." (PMID 33198737, 2020). "The Gln276Pro (rs1566734) and Arg326Gln (rs1503185) polymorphisms in PTPRJ are missense SNPs that were previously genotyped in colorectal, thyroid, lung, head and neck, oesophageal and breast cancers." (PMID 30661225, 2019). "Meta-analyses of a large breast cancer cohort revealed frequent loss of the PTPRJ locus, consistent with a tumor suppressor function and confirming loss of heterozygosity findings in a smaller cohort." (PMID 22815804, 2012). "The protein tyrosine phosphatase receptor J, PTPRJ, is a tumor suppressor gene that has been implicated in a range of cancers, including breast cancer, yet little is known about its role in normal breast physiology or in mammary gland tumorigenesis." (PMID 22815804, 2012). "Loss of heterozygosity (LOH) of PTPRJ has been detected in breast, lung and colon cancers and expression has been shown to induce differentiation and to inhibit growth of breast cancer cells, indicating a function as tumour suppressor gene." (PMID 19563644, 2009). "It has been demonstrated that PTPRJ is frequently lost in breast cancer, that expression is significantly lower than in normal breast tissue, and that low levels of expression are associated with poorer overall survival." (PMID 36611803, 2022). "Frequent deletion of PTPRJ, allelic imbalance in loss of heterozygosity (LOH), and missense mutations have been identified in human colon, lung, and breast cancers." (PMID 36611803, 2022). "The expression and localization of endogenous PTPRJ in a panel of human breast cancer cell lines was examined by western blotting and immunofluorescence." (PMID 22815804, 2012). "In summary, we have shown that PTPRJ is frequently lost in breast cancer, its expression is lower than normal breast and that low expression correlates with poorer overall survival." (PMID 22815804, 2012). "Another study has shown that the PTPRJ gene is a protective haploid in breast cancer." (PMID 36611803, 2022). "Genome wide association (GWA) studies has identified a specific PTPRJ breast cancer protective haplotype, however the causal SNP has not yet been determined." (PMID 22815804, 2012). "Since the overall levels of PTPRJ varied in the breast cancer lines, we tested whether ectopic expression of wildtype PTPRJ affected phenotype." (PMID 22815804, 2012). "Whilst the sample numbers in the study are small, a greater proportion of the grade 3 breast carcinoma exhibited exclusive cytoplasmic staining compared to grade 2, consistent with the loss of PTPRJ apical localisation concurrent with lack of tubular architecture." (PMID 22815804, 2012). "Therefore, although our findings are consistent with a tumor suppressor role for PTPRJ, PTPRJ loss does not appear to be driving a particular breast cancer phenotype." (PMID 22815804, 2012). "The mechanisms underlying the regulation of PTPRJ expression have not yet been explored, nor whether its dysregulation may contribute clinically to breast cancer progression, as would be expected from a tumor suppressor gene." (PMID 22815804, 2012). "Furthermore, no or only very weak associations were found between PTPRJ mRNA levels and tumor grade or molecular phenotype in two independent breast cancer cohorts (NKI-295 and Borg 359)." (PMID 22815804, 2012). "Breast cancer proliferative genes, such as aurora kinase, ERCC1, IGFBP3 were inhibited and growth inhibitory genes, such as NQO1, PTPRJ were activated by GTx-027." (PMID 25072326, 2014). "Thus, although PTPRJ protein expression was not consistently lost in breast cancer, loss of apical staining of PTPRJ may be associated with the level of differentiation within the tumor." (PMID 22815804, 2012).
breast carcinoma (continued). "Although loss of heterogeity has been reported for colon, lung, breast and thyroid cancers, we have not detected any major down-regulation of PTPRJ protein or mRNA in a large cohort of breast cancers." (PMID 23840844, 2013). "The localisation of PTPRJ is clearly an important feature of its function, yet to date, this has not been investigated in the normal breast or breast cancer samples." (PMID 22815804, 2012). "The role of PTPRJ in breast cancer and in normal breast biology is not well understood." (PMID 22815804, 2012).
colorectal cancer (12 papers, 2012 to 2022). A primary or metastatic malignant neoplasm that affects the colon or rectum. "PTPRJ is a candidate colorectal cancer susceptibility gene, and loss of PTPRJ is an early event in colorectal tumorigenesis and thyroid." (PMID 31384238, 2019). "In addition, a known pathogenic mutation of PTPRJ (p.Gln276Pro) (colorectal cancer) was also observed in 40.1% (20/49) GIST tumors." (PMID 34805171, 2021). "Moreover, germline epigenetic silencing of this gene in early-onset familiar colorectal cancer as well as the loss of PTPRJ expression in association with an advanced tumour stage and poor differentiation in oesophageal squamous cell carcinoma was described." (PMID 30661225, 2019). "PTPRJ is recognized as a tumor suppressor gene in colorectal carcinoma, breast tumors and even normal mammary epithelial cells, but the expression and function of PTPRJ in endothelial cells during angiogenesis has remained unclear." (PMID 25532119, 2014). "PTPRJ was first identified as a tumor suppressor gene and has been found to be decreasingly expressed in a variety of cancers, including gastric cancer, HCC, colorectal cancer, and cervical cancer." (PMID 36611803, 2022). "PTPRJ is recognized as a tumor suppressor gene in colorectal carcinoma but to date neither its role in normal development or tumorigenesis had been thoroughly investigated in breast." (PMID 22815804, 2012).
colon cancer (8 papers, 2009 to 2022). "Examples include two genes identified through mouse mapping studies: AURKA, which shows allele-specific gains of the T91A allele in human colon tumors and PTPRJ, which shows allele-specific losses of the A1176C allele in human colon tumors." (PMID 20885788, 2010). "Since reports connecting PTPRJ variants to colon cancer risk continue to appear we may hope that meta-analyses in a perhaps far future could settle the issue." (PMID 36755664, 2022). "In mice, the gene encoding PTPRJ was mapped to a colon cancer susceptibility locus (Scc1)." (PMID 33296397, 2020). "Moreover, mutation of PTPRJ (DEP1) has been indicated in breast, lung, thyroid and colon cancers." (PMID 23185569, 2012).
meningioma (8 papers, 2012 to 2024). A generally slow growing tumor attached to the dura mater. "The LOH of the PTPRJ gene and loss of PTPRJ protein expression were identified in a subpopulation of human meningiomas." (PMID 36611803, 2022). "PTPRJ polymorphisms were found to influence susceptibility to a variety of human cancers, e.g., thyroid, rectal colon cancers, meningiomas." (PMID 33692975, 2021). "DEP-1 (density-enhanced phosphatase-1, encoded by PTPRJ) is a tumor suppressor that plays a role in meningioma." (PMID 38879686, 2024). "Meningioma cells are inhibited by PTPRJ, and deletion of PTPRJ increases meningioma cell motility in vitro and invasive growth in an orthotopic xenograft model." (PMID 36611803, 2022). "PTPRJ plays a crucial role in tumor pathogenesis, and its expression is significantly reduced in some malignant tumors, such as human meningioma and breast, pancreatic, thyroid, colon, lung, and cervical carcinoma cancers." (PMID 36611803, 2022). "This suggests that the deletion of PTPRJ and Merlin contributes to the development of meningiomas; however, the exact mechanisms are still unknown." (PMID 36611803, 2022). "The negative regulation of PDGF receptor signaling and the positive regulation of adhesion signaling by PTPRJ cooperatively inhibited the motility of meningioma cells and may have suppressed tumor invasiveness." (PMID 36611803, 2022). "PTPRJ promotes cell adhesion and inhibits PDGFR signaling, and its loss may promote meningioma progression through interacting with NF2 loss." (PMID 35706047, 2022). "Additionally, deletion of PTPRJ promotes NF2-dependent meningioma development." (PMID 36611803, 2022).
Arthritis (5 papers, 2013 to 2025). Inflammation of a joint. "Among them, PECAM1 and PTPRJ were shown to play a role in the protection against arthritis and exert anti-fibrotic effects, respectively." (PMID 37205098, 2023).
gastric cancer (5 papers, 2009 to 2022). A primary or metastatic malignant neoplasm involving the stomach. "In silico analysis revealed that gene deletions or missense/truncated mutations of PTPRJ gene rarely occurred in gastric cancers." (PMID 32201537, 2020). "Since we detected missense mutations of this gene in the gastric cancer cell lines analyzed, it gives the indication that PTPRJ might play a role as tumour suppressor gene in gastric cancer, however, apparently not by inactivation by nonsense mutation." (PMID 19563644, 2009). "In PTPRJ, three mutations were detected in the UPF1 siRNA-transfected IPA220 gastric cancer cells." (PMID 19563644, 2009). "In the gene PTPRJ, three missense mutations were detected in IPA220 gastric cancer cell line." (PMID 19563644, 2009). "However, the knockdown or knockout of PTPRJ increased the ability of gastric cancer cells to grow and metastasize in vitro and in vivo, and suppression of PTPRJ expression resulted in poor clinical characteristics and a poor prognosis in patients with gastric cancer." (PMID 36611803, 2022). "Therefore, it is hypothesized that PTPRJ may be a potential predictor of prognosis in gastric cancer and that the study of PTPRJ as a potential therapeutic target for gastric cancer will be a future research direction." (PMID 36611803, 2022). "Furthermore, the 3′UTR region of the PTPRJ gene has high DNA methylation levels, and there is a strong association between these levels and PTPRJ expression, indicating that DNA methylation may be a significant regulator of PTPRJ expression levels in gastric cancer." (PMID 36611803, 2022). "The genes PLA2G4A, BMP5, MMP6, KNNMB4 and DYM were candidates for the GP202 gastric cancer cell line and the genes TXNL4B, FOXK1, PTPRJ, and SNN were candidates for the IPA220 gastric cancer cell line." (PMID 19563644, 2009).
lung fibrosis (5 papers, 2022 to 2024). "Some extracellular proteins such as SDC2 can bind to PTPRJ and activate its activity, reducing fibrosis levels in vivo as well as in vitro in lung fibrosis models, providing new ideas in the treatment of IPF." (PMID 36611803, 2022). "Tsoyi and other researchers found that PTPRJ is downregulated in clinical cases of Idiopathic Pulmonary Fibrosis (IPF) and that PTPRJ downregulation modulates the profibrotic response." (PMID 36611803, 2022).
Obesity (5 papers, 2013 to 2025). Accumulation of substantial excess body fat. "Thus, PTPRJ induction is implicated in the development of leptin resistance, and PTPRJ inhibition may be a potential strategy for improving obesity." (PMID 39897330, 2025). "Diet-induced obesity and leptin administration increase PTPRJ expression in the hypothalamus, and PTPRJ overexpression induces leptin resistance." (PMID 39897330, 2025). "Diet-induced obesity and the leptin treatment up-regulated PTPRJ expression in the hypothalamus, while the overexpression of PTPRJ induced leptin resistance." (PMID 28912580, 2017). "Thus, PTPRJ induction is a contributor to the development of leptin resistance, and suppression of PTPRJ may be a possible strategy for ameliorating obesity." (PMID 36611803, 2022). "Moreover, we found that the induction of PTPRJ may contribute to leptin resistance induced by obesity." (PMID 28912580, 2017). "Thus, the induction of PTPRJ is a factor contributing to the development of leptin resistance, and the inhibition of PTPRJ may be a potential strategy for improving obesity." (PMID 28912580, 2017).
Thrombocytopenia (5 papers, 2018 to 2025). A reduction in the number of circulating thrombocytes. "Whole exome sequencing performed in two siblings (1%) (9-year-old male and 17-year-old female) allowed us to identify two compound heterozygous mutations in PTPRJ gene, responsible for a novel form of thrombocytopenia." (PMID 36507135, 2022). "Moreover, two protein-truncating PTPRJ alleles (p.T38Pfs9* and p.S626Afs7*) have recently been discovered in a study towards genes underlying inherited thrombocytopenia and, importantly, functional studies in zebrafish and mouse models underscored the important role for PTPRJ in platelet biogenesis." (PMID 36755664, 2022). "A decade ago already, three PTPRJ polymorphisms (rs1566734, rs1503185 and rs4752904) were linked to human platelet reactivity and suggested to lower the risk of heparin-induced thrombocytopenia although this could not be confirmed in a French patient cohort." (PMID 36755664, 2022).
thyroid cancer (5 papers, 2013 to 2022). "In our meta-analysis, to our best knowledge, we analysed all published data for PTPRJ Arg326Gln and Gln276Pro polymorphisms in different cancers (breast, colorectal, oesophagus, head and neck, lung and thyroid cancer)." (PMID 30661225, 2019). "PTPRJ has been implicated in breast, colon, lung and thyroid cancers, and it is expressed by all resting leukocytes and upregulated following in vitro stimulation, thus it appears to be a T cell activating molecule." (PMID 26248682, 2016). "Furthermore, the PTPRJ loss of heterozygosity (LOH) was found to be more common in the thyroid carcinomas of heterozygotes for Gln276Pro and Arg326Gln than in homozygotes." (PMID 36611803, 2022).
bladder cancer (4 papers, 2015 to 2023). "However, PTPRJ was downregulated in the sEV fractions of the bladder cancer patients in this study and is also frequently deleted in several types of cancer." (PMID 37371512, 2023).